IL1B (interleukin 1 beta)
Diseases named in the same sentence as IL1B in open-access papers (continued):
Sharing a sentence is not in itself a finding about the gene and the disease.
retinal degeneration (continued). "Concordantly, IL-1β can induce apoptosis of retinal endothelium, neuronal precursor cells, and photoreceptors, but the precise mechanism of photoreceptor death in retinal degeneration remains unclear." (PMID 33246504, 2020). "However, opposing observations on the role of IL-1β in retinal degeneration have been reported." (PMID 33246504, 2020). "Furthermore, while it has been widely considered to be the predominant retinal cell type expressing the inflammasome, NLRP3 activation in the RPE has not been conclusively proven to be responsible for propagating IL-1β release and inflammatory-mediated cell death in retinal degenerations." (PMID 31379825, 2019). "In addition, the expression of IL-1β gene and protein is upregulated several fold in rodent retinas following photo-oxidative damage and inhibition of IL-1β using siRNAs or neutralizing antibodies suppressed chemokine-induced inflammation and retinal degeneration in AMD." (PMID 35576057, 2022). "We suggest that in retinal degenerations, CASP-1 propagates retinal inflammation and photoreceptor cell death via the cleavage and activation of pro-inflammatory cytokine IL-1β as well as possibly through its role in Gasdermin D pyroptotic pore formation." (PMID 32041990, 2020). "Finally, the complement cascade, comprised of three pathways to trigger the lysis of pathogens, apoptotic cells and clearance of foreign debris, may also be influenced by inflammasome signaling and may alter the level of IL-1β production in retinal degeneration." (PMID 31379825, 2019). "IL-1β is produced by retinal microglia and macrophages and promotes chemokine expression by Müller cells and RPE in retinal degeneration." (PMID 28438165, 2017). "The NaIO3-induced retinal degeneration mock group showed increased expression of Fas, inflammatory cytokines (TNF-α, IL-6, and IL-1β), MCP-1, and macrophages (F4/80), and an elevated M1 (CD11c)/M2 (CD206) macrophage ratio compared with that in the normal mouse group." (PMID 38534392, 2024). "IL-1β is another pro-inflammatory cytokine found to be upregulated during retinal degeneration, although photoreceptor cell death appears not to be directly mediated by IL-1β itself since photoreceptors poorly express its receptor IL-1R1." (PMID 38370034, 2024). "GSDMD mutant and knockout mice, in vitro models of inflammation and a well-established in vivo model of retinal degeneration (photo-oxidative damage; PD) were utilised to explore the role and pathological contribution of GSDMD in regulating IL-1β release and propagating retinal inflammation." (PMID 37864169, 2023). "However, our work indicated that, during the BLE-induced retinal degeneration, the NLRP3 inflammasome and the following IL-1β were mainly expressed in activated microglia." (PMID 27831552, 2016). "In comparison with normal controls, the mRNA levels of pro-inflammatory cytokines, including IL-1β, IL-6, TNF-α, and MCP-1 increased significantly higher in the MNU group (p < .01; n = 8), indicating that inflammation was involved in the pathogenesis of retina degeneration." (PMID 33501868, 2021). "In contrast to most recent literature, previous studies have reported a dose dependent effect of IL-1β, with low doses (5 μg/ml) conferring retinal protection and photoreceptor rescue in The Royal College of Surgeons (RCS) rats, a strain with inherited retinal degeneration." (PMID 31379825, 2019). "Rodent models of retinal degenerations including dry AMD and retinitis pigmentosa, support this notion, with IL-1β localization shown to be expressed primarily by infiltrating macrophages in the outer retina and subretinal space." (PMID 31379825, 2019).
temporal lobe epilepsy (36 papers, 2008 to 2025). A localization-related (focal) form of epilepsy characterized by recurrent seizures that arise from foci within the temporal lobe, most commonly from its mesial aspect. "Studies have shown more frequent genetic mutations in IL-1α and IL-1β genes in patients with temporal lobe epilepsy, and IL-1β in patients with febrile seizures compared with healthy controls." (PMID 35096712, 2021). "The increased frequency of biallelic polymorphisms in the promoter region of IL-1β at the -511 position were reported in patients with temporal lobe epilepsy with hippocampal sclerosis, and in prolonged febrile convulsion." (PMID 20021679, 2009). "In addition, the investigation of IL-1β- and IL-1R1- immunoreactivity in temporal lobe epilepsy with hippocampal sclerosis brain specimens supported the correlation of IL-1β signal to neuronal cell loss and BBB permeability alteration." (PMID 41155637, 2025). "Toll-like receptor 1 (TLR1) was also shown to be predictive of seizure frequency in our study and is implicated in temporal lobe epilepsy as a key transduction receptor of neuro- inflammation-induced epileptogenesis through glial production of inflammatory cytokines, IL-1β and TNF-α." (PMID 38166692, 2024). "For instance, SPIONs can be attached to the anti-IL-1β monoclonal antibody to be used for MRI diagnoses and targeted therapy by neutralizing IL-1β which is overexpressed in the epileptogenic area of an acute rat model with temporal lobe epilepsy, a disease in the brain associated with inflammation." (PMID 31185664, 2019). "Inhibition of NLRP3 attenuated localized brain damage in refractory temporal lobe epilepsy by downregulating IL-1β expression." (PMID 39091611, 2024). "Another magnetic-targeted drug delivery system with superparamagnetic iron oxide NPs and including an anti-interleukin-1β monoclonal antibody (anti-IL-1β mAb) was tested in an acute rat model of temporal lobe epilepsy." (PMID 36839629, 2023). "It is also reported that GPR120 downregulates neuroinflammation and alleviates epileptic seizure activity via NLRP3/Caspase-1/IL-1β signals in KA-induced temporal lobe epilepsy." (PMID 38187384, 2023). "Enhanced concentrations of IL-1β in epileptogenic brain tissue specimens of patients with temporal lobe epilepsy lowered GABA-mediated neurotransmission and stimulated the initiation of seizures." (PMID 35239805, 2022). "Accordingly, we have previously shown that IL-1β can decrease GABA currents amplitude in human drug-resistant temporal lobe epilepsy (TLE) by activation of IL-1β signaling." (PMID 35741692, 2022). "The increased expression of IL-1β was also observed in the brain tissue of TLE (temporal-lobe epilepsy) patients, compared with control tissue, especially in patients with hippocampal sclerosis." (PMID 35326336, 2022). "An increase in the abundance of individual proinflammatory molecules including interleukin 1 beta has been observed in brain tissue samples of patients with pharmacoresistant temporal lobe epilepsy (TLE) and corresponding animal models." (PMID 35972937, 2022). "An association between IL-1β gene polymorphisms and the risk of TLE (temporal lobe epilepsy) in individuals with TBI has been observed." (PMID 33377994, 2021). "In this study, NLRP3 and IL-1β were found to be involved in the occurrence and development of refractory temporal lobe epilepsy." (PMID 32116990, 2019). "IL-1β levels in the peripheral blood of patients with refractory temporal lobe epilepsy were significantly higher than those of the control group (t = 2.813, P = 0.01)." (PMID 32116990, 2019). "Increased levels of IL-1β and its receptor (IL-1R1) were found in samples from patients with temporal lobe epilepsy, and this increase was correlated with the frequency of seizures." (PMID 29921762, 2018).
temporal lobe epilepsy (continued). "This was first suggested by the upregulation of IL-1β in the hippocampi of chronically epileptic mice and in resected hippocampal tissue from patients with temporal lobe epilepsy." (PMID 27955671, 2016). "Recently, two proinflammatory molecules were found to be proconvulsant in animal models of temporal lobe epilepsy (TLE): IL-1β and HMGB1." (PMID 24936172, 2014). "Pro-inflammatory cytokines, NF-κB, interleukin (IL)-1β and its signaling receptor IL-1R1 are highly expressed by neurons and glia in temporal lobe epilepsy, focal cortical dysplasia, glioneuronal tumor, and in tuberous sclerosis complex." (PMID 20021679, 2009). "In human temporal lobe epilepsy, a variety of cytokines such as IL-1b, IL-6 and IL-ra are upregulated in the cerebrospinal fluid (CSF) in human temporal lobe epilepsy." (PMID 19787089, 2008). "Notably, elevated levels of IL-1β have been correlated with a reduced GABA-A currents in cases of temporal lobe epilepsy." (PMID 38078329, 2023). "The IL-1β levels in the peripheral blood of patients with refractory temporal lobe epilepsy may reflect the severity of convulsions." (PMID 32116990, 2019). "Moreover, other studies have shown that IL-1β regulates the PI3K/Akt/mTOR signalling pathway to generate mesio-temporal lobe epilepsy (MTLE)." (PMID 30514296, 2018). "In addition, overexpression of IL-1β may decrease the GABAA current (up to 30%) in temporal lobe epilepsy and rats with chronic epilepsy." (PMID 38187384, 2023). "Several inflammatory mediators, such as pro-inflammatory cytokines (IL-1β, IL-6, TNF-α) and transcriptional factor NFκB, were detected in brain tissue surgically resected from patients with temporal-lobe epilepsy (TLE)." (PMID 35326336, 2022). "A recently published paper further describes that the pathogenesis and maintenance of temporal lobe epilepsies are attributed to the activation of P2X7 receptors by the release of ATP during neurodegeneration, which activates the microglia to release IL-1β." (PMID 27875989, 2016). "IL-1β can also stimulate synaptophysin expression and epileptiform discharges via the PI3K/Akt/mTOR signaling pathway to induce seizure generation in an animal model with temporal lobe epilepsy." (PMID 35837232, 2022). "Our results demonstrate a HMGB1 and IL-1β-mediated environmental anti-neurogenic effect in human TLE, identifying both the IL-1R and TLR 2/4 receptors as potential drug targets for restoring human hippocampal neurogenesis in temporal lobe epilepsy." (PMID 34548070, 2021). "While, suppression of IL-1β or TNF-α expression could lead to prevention or delay of seizures, and exerts neuroprotection in a rat model of temporal lobe epilepsy." (PMID 29311813, 2017). "Moreover, inhibition of IL-1β or TNF-α expression may lead to prevention or delay of seizures and play a neuroprotective effect on a rat model of temporal lobe epilepsy." (PMID 32982679, 2020).
cerebral edema (35 papers, 2011 to 2025). "IL-1β is a known pro-inflammatory cytokine that induces cerebral inflammatory reaction and is associated with the development of cerebral edema in ICH rats." (PMID 34975411, 2021). "TBI-induced microglial activation and increased expression of inflammatory mediators (HMGB1, TNF-α, IL-1β, IL-6) in the brain have been associated with cerebral edema and neurological deficits." (PMID 32610502, 2020). "Previous studies have shown that reduced TNF-α and IL-1β caused a marked reduction in ischemic brain damage and cerebral edema." (PMID 24916922, 2014). "After brain injury, the expression of TNF-α, IL-6, IL-1β, and other inflammatory factors is up-regulated, which is closely related to the development of cerebral edema." (PMID 40584448, 2025). "Conversely, in dengue encephalitis, elevated levels of pro-inflammatory cytokines such as TNF-α and IL-1β can contribute to more generalized cerebral edema and hyperintensities in the thalamus and brainstem, often without restricted diffusion." (PMID 39737281, 2024). "MCC950 reduces IL-1β production, attenuates neurologic deficits and perihematomal brain edema, improves BBB integrity, and decreases pyroptosis after induction of ICH induction by injection of autologous blood or collagenase." (PMID 36131917, 2022). "As a pivotal regulator of the innate immune system, NLRP3 is activated after ICH, which can boost the inflammatory response by the release of IL-1β and facilitate neutrophil infiltration, thus radically exacerbating brain edema." (PMID 34413820, 2021). "Other inflammatory cytokines such as IL-6 and IL-1β and NF-κB activation play an important role in the pathogenesis of brain edema." (PMID 34795593, 2021). "The pro-inflammatory cytokine, interleukin-1β (IL-1β) as well as the proteolytic enzymes, matrix metalloproteinase-9 (MMP-9) are key mediators of trauma-associated brain edema." (PMID 27152411, 2016). "Many experimental data have revealed that expression of IL-1β and TNF-a increase after ICH, and are associated with brain edema and brain damage." (PMID 24289479, 2013). "Increased expression of the pro-inflammatory cytokine, IL-1β, clinically correlates with the development of cerebral edema after brain injury." (PMID 22815977, 2012). "Dexamethasone inhibits the production of TNF-α and IL-1β, reduces brain edema, and limits the increase in cerebrospinal fluid lactate and leukocyte concentrations." (PMID 22191010, 2011). "Inflammatory cells release pro-inflammatory cytokines (e.g., TNF-α, IL-1β, IL-6), chemokines, and reactive oxygen species (ROS), which further exacerbate neuronal apoptosis, blood-brain barrier disruption, and cerebral edema, and aggravate neurological deficits." (PMID 41451361, 2025). "Studies have shown that dexamethasone, commonly used for the management of cerebral edema, inhibits TAM production of IL-1β, and genetic ablation of IL-1α/β or IL-1β in a murine GB model or the administration of a potential IL-1β inhibitor (Sulfasazaline) reduces cerebral edema." (PMID 37355636, 2023). "Moreover, it inhibited NF-κB DNA-binding activity, reduced expression of inflammatory molecules (TNF-α, IL-1β, IL-6) and ameliorated locomotor function as evident by beam walking performance, along with cerebral edema and cortical apoptotic cell death." (PMID 32610502, 2020). "It was suggested that the relationship between NKCC1 and pro-inflammatory cytokines, such as TNF-α and IL-1β, may be one of the key factors of cerebral edema." (PMID 24916922, 2014). "After traumatic brain injury (TBI), Cerebrolysin enhances neurological scores, lowers cerebral edema, improves BBB permeability, and reduces inflammatory cytokines such as TNF-α, IL-1β, IL-6, and NF-κB." (PMID 40362194, 2025). "Our data show that piperine treatment can reduce the degree of cerebral edema, down-regulate TNF-α, IL-1β, and BDNF, decrease the reactivity of GFAP in the hippocampus, and inhibit TBI-induced seizures." (PMID 32655468, 2020).
cerebral edema (continued). "Activation of microglia and astrocytes and overexpression of the pro-inflammatory factor IL-1β and inflammatory mediators were mediated via NF-κB signaling pathway during the course of 1,2-DCE-induced brain edema in mice." (PMID 31461951, 2019). "In our study, ICT treatment decreased the expression of IL-1β and TNF-α while increasing the level of IL-10, indicating that ICT inhibited neuroinflammation and cerebral edema induced by tMCAO in rats by decreasing proinflammatory cytokine levels and increasing anti-inflammatory cytokine levels." (PMID 36447154, 2022). "In addition, IL-1β also promoted the expression of itself and the inflammatory mediators, as well as activation of microglia through the p38 MAPK/ NF-κB signaling pathway during the course of 1,2-DCE-induced brain edema in mice." (PMID 31461951, 2019). "However, IL-1β might not be directly involved in overexpression of iNOS, and activation of astrocytes during the course of 1,2-DCE-induced brain edema in mice." (PMID 31461951, 2019). "However, whether IL-1β also plays a role in activation of p38 MAPK/ NF-κB signaling pathway during the course of 1,2-DCE-induced brain edema in mice is not known." (PMID 31461951, 2019).
joint disease (35 papers, 2005 to 2025). "It is known that the activation of the NLRP-3 inflammasome and the production of IL1-β play important roles in the pathophysiology of hydroxyapatite-associated arthropathy." (PMID 38397865, 2024). "Muscle and joint diseases were associated with increased IL-1β, MMP-8 and the ratio MMP-8/TIMP-1." (PMID 23637817, 2013). "In fact, worsening of joint disease was associated with a marked increase of local proinflammatory cytokines (IL-6, IL-1β, and TNF-α) responsible for articular damage, together with sustained levels of monokines and a consequent enhanced inflammatory cell influx." (PMID 19606256, 2009). "Neutrophilic skin or joint disease favors assessment with IL-17/23 panels, while crystal arthropathies or recurrent inflammatory flares warrant IL-1β, urate, and NLRP3 inflammasome profiling." (PMID 41440484, 2025). "Despite the apparent limitations of a cell model to study a joint disease that has also been described as a systemic disease, we still obtained preliminary results using IL-1β-treated SW1353 chondrocytes to mimic the inflammatory environment found in OA." (PMID 36253872, 2022). "Gene expression analysis showed a reduction in the expression of some inflammatory joint disease markers, such as Aggrecan and types I and II Collagen, after extract and IL-1β treatment." (PMID 33072083, 2020). "Moreover, markers associated with low inflammation levels, such as TNF-α, IL-6, and IL-1β, are under extensive investigation and are proposed as discriminators between OA and other joint disorders characterized by a severe inflammatory component." (PMID 38785519, 2024). "Because IL-1β is the major cytokine associated with joint disease, this also suggests that dietary SDP’s observed improvement of articular ROM may be explained by the reduced expression of pro-inflammatory IL-1β." (PMID 33748684, 2021). "Nonetheless, inflammatory cytokines IL-1β and MMPs also play key roles in major joint diseases." (PMID 31137797, 2019). "We corroborated these results by measuring cytokine concentrations in synovial lavage fluid and in plasma samples and show that TRPC5 deletion or antagonism increased the local secretion of a number of critical pro-inflammatory cytokines (eg, TNFα, IL-1β) with an established role in joint disease." (PMID 27165180, 2017). "In the present study we investigated first the respective time courses of prostaglandin production and induction of genes of the arachidonic acid cascade in chondrocytes activated with IL-1β, a pro-inflammatory cytokine with a central function in joint diseases." (PMID 16277686, 2005). "Additionally, the production of IL‐1β decreased, while IL‐10 levels increased in joint effusion." (PMID 41255239, 2025). "The elevated levels of IL-1β, IL-6, and TNF-α, as well as of MMPs, found in the SF of both OA and RA patients confirmed their important role in the pathogenesis of these joint diseases." (PMID 35955467, 2022). "Pyrophosphate and monosodium urate monohydrate (MSUM) crystals responsible for acute and chronic crystal arthropathies were identified as danger signals activating the caspase-1-activating NALP3 inflammasome, inducing pro-IL-1β maturation in macrophages." (PMID 25436167, 2014). "We therefore isolated FLS from portions of synovial tissues from patients experiencing inflammation and other symptoms of joint disease, and the FLS were then stimulated with IL-1β in an in vitro condition simulating synovitis." (PMID 23331485, 2013). "The levels of IL-1β, IL-8 and MMP-8, as well as the MMP-8/TIMP-1 ratio were higher in subjects with muscle and joint diseases." (PMID 23637817, 2013). "IL-1β was used as a marker and stimulator to induce human peripheral blood lymphocytes (RPMI1788) and human fibroblast synovial cells (HFLS), which provided excellent indicators for the development of joint diseases and inflammation." (PMID 35795138, 2022).